HLA-C (major histocompatibility complex, class I, C)
Diseases named in the same sentence as HLA-C in open-access papers (continued):
Sharing a sentence is not in itself a finding about the gene and the disease.
cutaneous melanoma (3 papers, 2020 to 2025). A primary melanoma arising from atypical melanocytes in the skin. "As already shown by our group and others, a decreased expression of several HLA class I APM components, such as TAP1, HLA-A, HLA-B and HLA-C, has been associated with poor patient survival in several types of cancer, including cutaneous melanoma." (PMID 32825219, 2020).
Hepatitis B (3 papers, 2013 to 2022). "Further studies are needed either to establish an independent effect of KIR2DL3 in hepatitis B infection or to confirm the protective effect of KIR2DL3/HLA-C combinations." (PMID 29149205, 2017).
male infertility (3 papers, 2020 to 2023). The inability of the male to effect fertilization of an ovum after a specified period of unprotected intercourse. "The worst combination of KIR and HLA-C for male infertility is CenAB/TelBB/C2+, where the KIR2DS1, KIR2DS5, and KIR3DS1 genes are also present." (PMID 38201263, 2023). "Potential integrations between activating KIR receptors in CenAB + BB carriers and HLA-C allotypes may influence male infertility, while carriers of the KIR CenAA genotype do not experience problems with conception." (PMID 38201263, 2023).
periodontitis (3 papers, 2022 to 2026). An acute or chronic inflammatory process that affects the tissues that surround and support the teeth. "MR analysis demonstrated a significant positive correlation between HLA-C expression levels and periodontitis, suggesting that HLA-C may be a potential risk factor." (PMID 40692979, 2025). "SNPs in HLA-C were significantly and positively associated with the risk of periodontitis, suggesting that HLA-C may serve as a genetic susceptibility factor for the disease." (PMID 40692979, 2025). "We then further investigated the causal relationship between HLA-C and periodontitis." (PMID 40692979, 2025). "MR analysis further confirmed the causal relationship between HLA-C and periodontitis." (PMID 40692979, 2025). "The findings indicate that HLA-C not only exhibits a causal relationship with the onset of periodontitis but may also play a key role in immune regulation by modulating the activity of plasma cells and other immune cells, as well as their intercellular interactions." (PMID 40692979, 2025). "Among them, HLA-C (IVW, nine SNPs, p=0.03) was identified as a risk factor for periodontitis, while STAP1 (IVW, four SNPs, p=0.01) and PTP4A3 (IVW, 10 SNPs, p=0.04) were recognized as protective factors." (PMID 40692979, 2025). "In conclusion, this study highlights the critical role of HLA-C in the immune response of periodontitis, particularly in immune cell infiltration and intercellular interactions." (PMID 40692979, 2025). "scRNA-seq analysis confirmed these findings, showing a marked increase in plasma cell numbers, significantly upregulated HLA-C expression in plasma cells, and enhanced intercellular communication in periodontitis patients." (PMID 40692979, 2025). "It offers new insights into the molecular mechanisms of periodontitis and provides a theoretical basis for the development of HLA-C-targeted therapeutic agents." (PMID 40692979, 2025). "This study combines DEG, WGCNA, immune cell infiltration assessment, scRNA-seq, and MR analysis to reveal the pivotal role of the HLA-C gene in periodontitis." (PMID 40692979, 2025). "MD analysis revealed a strong binding affinity between metronidazole and HLA-C, suggesting its potential as a therapeutic drug and providing new directions for the treatment of periodontitis." (PMID 40692979, 2025). "Additionally, cellular experiments will be conducted to evaluate the functional impact of HLA-C–metronidazole interactions on immune cell activity and periodontitis progression." (PMID 40692979, 2025). "Further investigation revealed that key genes, including human leukocyte antigen C (HLA-C), STAP1, PTP4A3, NEU1, IGLV1-44, IGLL5, and NIPAL4, play critical roles in the pathogenesis of periodontitis." (PMID 40692979, 2025).
Achalasia (2 papers, 2018 to 2024). A disorder of esophageal motility characterized by the inability of the lower esophageal sphincter to relax during swallowing and by inadequate or lacking peristalsis in the lower half of the body of the esophagus. "Regarding the HLA-C locus, the most common alleles in the achalasia patients were C*07:02, C*04:01 and C*12:03, whereas in the controls, the most common alleles were C*07:02, C*04:01 and C*01:02." (PMID 30092016, 2018). "In this study, we classified HLA class I (HLA-C/-B) and class II (HLA-DRB1/-DQB1) blocks according to their most probable ancestry (MPA) in both the achalasia group and the control group." (PMID 30092016, 2018).
acute lymphoblastic leukaemia (2 papers, 2022 to 2024). "Participants in UKALL14 had B-cell or T-cell acute lymphoblastic leukaemia, were aged 25–65 years (BCR-ABL1-negative) or 18–65 years (BCR-ABL1-positive), and for this subcohort had a fit, matched sibling donor or an 8 out of 8 allelic matched unrelated donor (HLA-A, HLA-B, HLA-C, and HLA-DR)." (PMID 35358442, 2022).
Burkitt lymphoma (2 papers, 2021 to 2024). A rare form of malignant mature B-cell non-Hodgkin lymphoma. "Particularly, HLA-C*06:02 was identified as having a protective role against Burkitt lymphoma, while HLA-C*12:02 was positively associated with PTLC-NOS." (PMID 38535155, 2024).
diffuse large B-cell lymphoma (2 papers, 2021 to 2023). "While risk of diffuse large B-cell lymphoma and marginal zone lymphoma were increased with homozygosity of class I HLA-B and HLA-C loci and the class-II HLA-DRB1 locus, follicular lymphoma risk was associated with the increase in homozygous loci for HLA class II genes." (PMID 37942321, 2023).
Ebola (2 papers, 2018 to 2024). "If indeed Ebola-GP does not shield membrane-associated HLA-C, then it will not interfere with the HLA-C-KIR2DS1 interaction (HLA-C2 allele is the target for KIR2DS1)." (PMID 30013549, 2018).
ependymoma (2 papers, 2023 to 2025). A WHO grade II, slow growing tumor of children and young adults, usually located intraventricularly. "For HLA-B, frequencies ranged from 0% in ependymoma to 31% (5 out of 16) in aHGG models, while the homozygosity frequencies of HLA-C ranged from 11% (2 out of 19) in neuroendocrine to 36% (12 out of 36) in bone and soft tissue sarcoma models." (PMID 41312385, 2025).
gastritis (2 papers, 2024 to 2025). Inflammation of the stomach. "Others included 41 GWS genes for GERD (Pgene-GERD < 2.62 × 10−6), 11 for PUD (Pgene-PUD < 2.62 × 10−6), three (RNF5, HLA-DQA1, and HLA-DQB1) for gastritis-duodenitis (Pgene-gastritis-duodenitis < 2.62 × 10−6), and three (HLA-C, PITPNM2, and MPHOSPH9) for IBS (Pgene-IBS < 2.62 × 10−6)." (PMID 38802514, 2024).
head and neck cancer (2 papers, 2015 to 2020). A primary or metastatic malignant neoplasm affecting the head and neck. "Finally, high expression of HLA-A or HLA-C is a favorable factor for head and neck cancer patients, which is as this correlates with increased antigen presentation leading to immune-mediated tumor clearance." (PMID 33173143, 2020). "Note also that HLA-C has been recently identified as a likely driver in head and neck cancer." (PMID 26485003, 2015).
hepatoblastoma (2 papers, 2022 to 2024). Hepatoblastoma (HB) is a malignant hepatic tumor and is the most common pediatric liver cancer. "The abundance of NK cells, along with their surface inhibitory receptor KIR2DL, is elevated in patients with hepatoblastoma, potentially because the HLA‐C molecules on tumour cells bind to KIR2DL and suppress NK cytotoxicity, which leads to cancer cell immune escape." (PMID 38527290, 2024). "In hepatoblastoma, the interaction between HLA-C molecules and KIR2DL4 may be the mechanism by which tumor cells regulate the antitumor activity of NK cells, leading to tumor immune escape." (PMID 36507493, 2022).
liver cancer (2 papers, 2011 to 2013). An epithelial or non-epithelial malignant neoplasm that arises from the liver.
myelodysplastic syndrome (2 papers, 2022 to 2023). A clonal hematopoietic disorder characterized by dysplasia and ineffective hematopoiesis in one or more of the hematopoietic cell lines. "In vitro-stimulated NKG2C+ NK cells exhibit high cytotoxicity efficiency against HLA-C-mismatched primary ALL, AML, and myelodysplastic syndrome (MDS) blasts ex vivo, demonstrating the strong alloreactivity of NKG2C+ NK cells." (PMID 37144558, 2023).
myelogenous leukemia (2 papers, 2013 to 2021). "To finally prove HLA allo-reactivity of the TCR1376 to HLA-C*07, we performed co-culture with the HLA-deficient myelogenous leukemia cell line K562 that had been transduced with HLA-C*07:01, HLA-C*07:02, and HLA-A*02:01 molecules, respectively." (PMID 33875134, 2021). "Notably, HLA-C allele matching (four-digit level) had differential effects in HLA-C1 (C1/C1) and HLA-C2 (C1/C2 and C2/C2) subgroups of patients: in HLA-C1 patients with myeloid leukemia, HLA-C-matching was associated with improved survival." (PMID 23404428, 2013).
narcolepsy (2 papers, 2010 to 2019). A sleep disorder characterized by a tendency for excessive sleepiness during the day which occurs even after adequate sleep in the nighttime. "The HLA-I molecules were chosen based on reported associations with narcolepsy in two independent studies, i.e., HLA-A*11:01, HLA-B*18:01, B*35:01, B*51:01, and HLA-C*04:01." (PMID 30783092, 2019).
ocular toxoplasmosis (2 papers, 2015 to 2020). Ocular toxoplasmosis is an infection in the eye caused by the parasite, Toxoplasm a gondii. "The association between MICA and ocular toxoplasmosis was observed only when the linkage disequilibrium between the HLA-B and HLA-C loci was analysed." (PMID 26672749, 2015). "The MICA*002~HLA-B*35 haplotype was associated with increased risk of developing ocular toxoplasmosis, while the MICA*008~HLA-C*07 haplotype was associated with protection against the ocular manifestations of toxoplasmosis." (PMID 26672749, 2015).
periodontal disease (2 papers, 2014 to 2025). "Additionally, the results showed elevated HLA-C expression in periodontal disease samples, particularly in plasmablasts." (PMID 40692979, 2025).
prostate tumors (2 papers, 2016 to 2022). "Notably, the probe located within 50 bp upstream of the transcription start site for both HLA-A and HLA-C had the most significant increase in methylation in prostate tumors compared to normal samples." (PMID 36050516, 2022).
subacute thyroiditis (2 papers, 2023 to 2024). Self-limited inflammation of the thyroid gland characterized by the presence of multinucleated giant cells. "Interestingly, a strong association between HLA-C*04:01 and subacute thyroiditis (SAT) has been demonstrated in Caucasians, in addition to the previously known correlation between SAT and HLA-B*35." (PMID 39768617, 2024). "Interestingly, in the same study, we demonstrated a protective effect of HLA-C*04:01 allele, which was previously reported as related to increased risk of subacute thyroiditis (SAT)." (PMID 37841270, 2023).
vitamin D deficiency (2 papers, 2018 to 2024). A nutritional condition produced by a deficiency of VITAMIN D in the diet, insufficient production of vitamin D in the skin, inadequate absorption of vitamin D from the diet, or abnormal conversion of vitamin D to its bioactive metabolites. "Furthermore, a possible correlation between HLA-C gene methylation and vitamin D deficiency was identified, emphasizing the necessity for comprehensive analyses of the entire epigenome." (PMID 39257885, 2024).
alcohol (1 paper, 2019). "In the present study, we sought to identify differential AS events and corresponding genes in HBV-, HCV-, and alcohol-associated HCCs, and found intron 5 of HLA-C had a lower PSI level specifically in HBV-associated HCC than in the other groups." (PMID 31856847, 2019). "Intron retention of HLA-A was observed more frequently in HBV-associated HCC than HCV- or alcohol-associated HCC, and intron retention of HLA-C showed vice versa." (PMID 31856847, 2019).
alopecia areata (1 paper, 2023). Loss of scalp and body hair involving microscopically inflammatory patchy areas. "Alopecia areata is a disease caused by genetic and epigenetic immune irregularities, but the presence of C*04:01 and C*15:02 alleles of HLA-C predisposes this pathology in the Japanese population." (PMID 37465164, 2023). "Also, within the immunity spectrum, HLA-C has been linked to transplant rejection and skin diseases like alopecia areata or Crohn’s Disease, all related to an increased expression of this gene." (PMID 37465164, 2023).
anaphylaxis (1 paper, 2025). An acute hypersensitivity reaction that occurs from exposure to an allergen. "HLA association analysis identified HLA‐B*07:02 as a potential risk allele and HLA‐C*01:02 as a possible protective allele in cefaclor‐induced anaphylaxis." (PMID 40974473, 2025). "In contrast, HLA‐C*01:02 appeared to have a protective effect, being present in 4 anaphylaxis cases and 14 tolerant controls (p = 0.033; OR = 0.27; 95% CI, 0.06–0.99)." (PMID 40974473, 2025).
anxiety disorder (1 paper, 2022). A category of psychiatric disorders which are characterized by anxious feelings or fear often accompanied by physical symptoms associated with anxiety. "In the case of individuals with emotional distress at a medium or high level, the presence of alleles -HLA-A*32, HLA-B*52, and HLA-C*12 was predominantly observed, which could indicate that individuals who are carriers of these alleles have a higher risk of developing anxiety disorders." (PMID 36231907, 2022).
Ascites (1 paper, 2023). Accumulation of fluid in the peritoneal cavity (between the layers of the peritoneum that lines the abdomen). "Subsequently, a frequency analysis of HLA-C epitopes and genotypes was performed in AC patients according to the degree of ascites." (PMID 37760846, 2023). "The aim of this study was to analyze the KIR/HLA-C genetic profile in AC patients with and without ascites to clarify the understanding of this pathology and find predictive clinical susceptibility biomarkers that can help to establish risks and prevent ascites development in AC patients." (PMID 37760846, 2023). "The aim of this study was to analyze the KIR/HLA-C genetic profile in AC patients with and without ascites to understand this pathology and find predictive clinical susceptibility biomarkers that can help to establish risks and prevent the development of ascites in AC patients." (PMID 37760846, 2023). "Due to the importance of these Asn and Lys epitopes in the interaction of the HLA-C genotype as a ligand for KIR receptors, the possible influence of the presence of these epitopes in AC patients and controls was studied, as well as their influence on the presence of AC and ascites." (PMID 37760846, 2023). "This study aimed to analyze the KIR/HLA-C genetic profile in AC patients with and without ascites to clarify the understanding of this pathology and find predictive clinical susceptibility biomarkers that can help to establish risks and prevent ascites development in AC patients." (PMID 37760846, 2023).
bronchiectasis (1 paper, 2018). Segmental, irreversible dilation of the bronchial tree resulting in the accumulation of secretions which leads to obstruction. "A subsequent study demonstrated a lack of association between KIR and HLA-C type and susceptibility to idiopathic bronchiectasis." (PMID 29744361, 2018).
childhood asthma (1 paper, 2025). "However, our findings did not reveal any associations between the 6p.21 region (HLA‐B, HLA‐C, HLA‐DQA1, and HLA‐DQB) and childhood asthma, despite previous reports suggesting such an association." (PMID 40133993, 2025).
chronic lymphocytic leukemia (1 paper, 2018). "An association study found 6 protective or predisposing HLA-C alleles for chronic lymphocytic leukemia (CLL) in whites." (PMID 30155344, 2018).
diverticular disease (1 paper, 2024). A complex disorder characterised by mucosal outpouchings (diverticulae) of the colonic wall which can become infected and inflamed leading to diverticulitis, perforation and bleeding. "Similarly, we found 24 GWS (Pgene-diverticular-disease < 2.62 × 10−6) genes for diverticular disease, two for IBS (Pgene-IBS < 2.62 × 10−6, HLA-C and PITPNM2), and 26 for IBD (Pgene-IBD < 2.62 × 10−6) that were associated with T2D (Pgene-T2D < 0.05)." (PMID 38802514, 2024).
Embryonal tumors (1 paper, 2025). "Embryonal tumors (ATRT, ETMR, MRT, and medulloblastoma) were with similarly low expression levels, with medians spanning 6.0–7.2 for HLA-A, 3.9–6.5 for HLA-B, and 5.9–8.0 for HLA-C, indicating limited HLA class I-mediated immune visibility." (PMID 41312385, 2025).
Emphysema (1 paper, 2021). "Emphysema was also present in 31% of SC, and neither HLA-C*07 nor HLA-C*12 was significantly associated with the presence or severity of this abnormality (data not shown)." (PMID 34464355, 2021).
Flavivirus Infections (1 paper, 2011). Infections with viruses of the genus FLAVIVIRUS, family FLAVIVIRIDAE. "Of the various alleles reported as associated with neurological diseases or flavivirus infection, only HLA-C*08 allele was also found to be associated with symptomatic WNV infection in our study." (PMID 21829673, 2011).
idiopathic inflammatory myopathy (1 paper, 2023). Idiopathic form of inflammatory myopathy. "A study of the Japanese population found that the HLA-C*12:02 allele protects against a muscle disorder known as idiopathic inflammatory myopathy, in which HLA-C and other members of the major histocompatibility complex class I are highly expressed in the affected necrotic myofibers." (PMID 37465164, 2023).
IgG4-related pancreatitis (1 paper, 2023). "Another study by another Japanese group found six HLA class-associated variants, namely rs1143146 (HLA-A), rs1050716 (HLA-C), c.759_763delCCCCCinsTCCCG (HLA-C), rs1050451 (HLA-C), rs4154112 (HLA-DQB1), and rs1049069 (HLA-DQB1), to be associated with the relapse of IgG4-related pancreatitis." (PMID 36609529, 2023).
infectious mononucleosis (1 paper, 2022). A condition characterized by an increase in mononuclear white blood cells and swollen lymph nodes, which is usually caused by infection with the Epstein-Barr virus. "According to a previous study, HLA‐C*04:01 was associated with an increased risk of infectious mononucleosis, whereas HLA‐C*02:02 was associated with a reduced risk in students with asymptomatic seroconversion to EBV." (PMID 35759244, 2022).
laryngeal carcinoma (1 paper, 2022). Carcinoma that arises from the laryngeal epithelium. "Compared with three OSCC cell lines and one laryngeal carcinoma cell line, protein expression of HLA-A/B and HLA-C were significantly diminished." (PMID 36611830, 2022).
lepromatous leprosy (1 paper, 2013). A chronic communicable infection which is a principal or polar form of leprosy. "When groups were stratified, HLA-B*35 and HLA-C*04 were shown to be protective against lepromatous leprosy, while HLA-C*07 was shown to be a susceptibility variant." (PMID 23936864, 2013).
Löfgren’s syndrome (1 paper, 2023). "HLA-B*08:01, HLA-C*07:01, HLA-DRB1*03:01, HLA-DQA1*05:01, and HLA-DQB1*02:01 variants associated with Löfgren’s syndrome, a more benign phenotype." (PMID 37153085, 2023).
lymphoproliferative disorders (1 paper, 2024). "In these groups of genes, we identified two strong associations between HLA-C*02:02 (p = 0.002, OR = 1.101) and HLA-C*12:02 (p = 0.002, OR = 1.101) and lymphoproliferative disorders." (PMID 38535155, 2024). "A key finding of our study was the connection we established between HLA-C genes and lymphoproliferative disorders." (PMID 38535155, 2024).